CLU (clusterin)
Description:
[Isoform 1]: Functions as extracellular chaperone that prevents aggregation of non native proteins. Prevents stress-induced aggregation of blood plasma proteins. Inhibits formation of amyloid fibrils by APP, APOC2, B2M, CALCA, CSN3, SNCA and aggregation-prone LYZ variants (in vitro). Does not require ATP. Maintains partially unfolded proteins in a state appropriate for subsequent refolding by other chaperones, such as HSPA8/HSC70. Does not refold proteins by itself. Binding to cell surface receptors triggers internalization of the chaperone-client complex and subsequent lysosomal or proteasomal degradation. Protects cells against apoptosis and against cytolysis by complement: inhibits assembly of the complement membrane attack complex (MAC) by preventing polymerization of C9 pore component of the MAC complex. Intracellular forms interact with ubiquitin and SCF (SKP1-CUL1-F-box protein) E3 ubiquitin-protein ligase complexes and promote the ubiquitination and subsequent proteasomal degradation of target proteins. Promotes proteasomal degradation of COMMD1 and IKBKB. Modulates NF-kappa-B transcriptional activity. A mitochondrial form suppresses BAX-dependent release of cytochrome c into the cytoplasm and inhibit apoptosis. Plays a role in the regulation of cell proliferation. An intracellular form suppresses stress-induced apoptosis by stabilizing mitochondrial membrane integrity through interaction with HSPA5. Secreted form does not affect caspase or BAX-mediated intrinsic apoptosis and TNF-induced NF-kappa-B-activity. Secreted form act as an important modulator during neuronal differentiation through interaction with STMN3 (By similarity). Plays a role in the clearance of immune complexes that arise during cell injury (By similarity). [Isoform 6]: Does not affect caspase or BAX-mediated intrinsic apoptosis and TNF-induced NF-kappa-B-activity. [Isoform 4]: Does not affect caspase or BAX-mediated intrinsic apoptosis and TNF-induced NF-kappa-B-activity. Promotes cell death through interaction with BCL2L1 that releases and activates BAX.
Synonyms: Apo-J; CLI; SGP-2; TRPM-2; APOJ; KUB1; AAG4; SP-40; CLU1; CLU2; NA1/NA2; SGP2
Tractability: Antibody: UniProt places it where antibodies can reach, with high confidence; its Gene Ontology location is reachable by antibodies, with high confidence; UniProt predicts a signal peptide or a membrane-spanning region. PROTAC: UniProt records ubiquitination sites on it; ubiquitination databases record sites on it; its protein half-life has been measured.
Gene: Protein-coding gene on chromosome 8 (27,596,917 to 27,615,056, reverse strand). Ensembl gene ENSG00000120885.
Subcellular location: Secreted (Isoform 1); Cytoplasm (Isoform 4); Cytoplasm (Isoform 6); Nucleus; Cytoplasm; Mitochondrion membrane; Cytoplasm, cytosol; Microsome; Endoplasmic reticulum; Mitochondrion; Cytoplasm, perinuclear region; Cytoplasmic vesicle, secretory vesicle, chromaffin granule
Subcellular location (Human Protein Atlas): Cytosol; Predicted to be secreted
Pathways (Reactome):
Immune System: Antimicrobial peptides; Regulation of Complement cascade; Terminal pathway of complement
Disease: Dengue virus activates/modulates innate and adaptive immune responses
Hemostasis: Platelet degranulation
Gene Ontology:
Molecular function: amyloid-beta binding; ATP hydrolysis activity; low-density lipoprotein particle receptor binding; misfolded protein binding; protein binding; protein carrier chaperone; protein sequestering activity; protein-containing complex binding; receptor ligand activity; signaling receptor binding; tau protein binding; ubiquitin protein ligase binding; protein-folding chaperone binding
Biological process: amyloid-beta clearance; cell morphogenesis; central nervous system myelin maintenance; chaperone-mediated protein complex assembly; microglial cell activation; microglial cell proliferation; negative regulation of activation of membrane attack complex; negative regulation of amyloid fibril formation; negative regulation of amyloid-beta formation; negative regulation of complement activation; negative regulation of complement-dependent cytotoxicity; negative regulation of intrinsic apoptotic signaling pathway in response to DNA damage; negative regulation of protein-containing complex assembly; negative regulation of response to endoplasmic reticulum stress; positive regulation of neurofibrillary tangle assembly; positive regulation of nitric oxide biosynthetic process; positive regulation of proteasomal ubiquitin-dependent protein catabolic process; positive regulation of protein-containing complex assembly; positive regulation of receptor-mediated endocytosis; positive regulation of tumor necrosis factor production; positive regulation of ubiquitin-dependent protein catabolic process; protein folding; protein import; protein stabilization; protein targeting to lysosome involved in chaperone-mediated autophagy; and 17 more
Cellular component: apical dendrite; blood microparticle; cell periphery; cell surface; cytoplasm; cytoskeleton; cytosol; endoplasmic reticulum; extracellular exosome; extracellular region; intracellular membrane-bounded organelle; membrane; mitochondrial inner membrane; mitochondrial membrane; mitochondrion; neurofibrillary tangle; nucleus; perinuclear endoplasmic reticulum lumen; perinuclear region of cytoplasm; plasma membrane; protein-containing complex; spherical high-density lipoprotein particle; Golgi apparatus; platelet alpha granule lumen; chromaffin granule; and 1 more
Genetic constraint (gnomAD): Loss-of-function variants: 26 observed, 50.38 expected, observed/expected ratio (o/e) 0.52, 90% interval 0.38 to 0.72. The upper end of that interval is the gene's LOEUF score, 0.72, which puts it in group 2 of 6, group 1 being the genes least tolerant of losing a copy. Missense variants: 504 observed, 622.97 expected, observed/expected ratio (o/e) 0.81, 90% interval 0.75 to 0.87. Synonymous variants: 235 observed, 247.19 expected, observed/expected ratio (o/e) 0.95, 90% interval 0.85 to 1.06.
Homologues: Orthologues: chimpanzee CLU (98% identical), macaque CLU (95% identical), dog CLU (77% identical), rabbit CLU (77% identical), rat Clu (77% identical), guinea pig CLU (77% identical), mouse Clu (76% identical), pig CLU (71% identical), tropical clawed frog clu (42% identical), zebrafish clu (39% identical). Paralogues in human: CLUL1 (25% identical).
Diseases named in the same sentence as CLU in open-access papers:
CLU is named in the same sentence as 388 diseases in open-access papers, as found by Europe PMC text mining. Sharing a sentence is not in itself a finding about the gene and the disease. The quoted sentences say what the papers report.
Alzheimer disease (177 papers, 2008 to 2026). A progressive, neurodegenerative disease characterized by loss of function and death of nerve cells in several areas of the brain leading to loss of cognitive function such as memory and language. "ApoE and ApoJ (known also as clusterin) are associated with the development of neurodegenerative diseases, including Alzheimer’s disease, and are also important determinants of the lipid profile and cardiovascular health." (PMID 40137160, 2025). "The expression of EPHX2 was also found to be modified by other Alzheimer’s disease-related factors, such as the activity of the rs2279590 variant of the clusterin (CLU) gene, as well as obesity, a recognized risk factor for dementia." (PMID 41007636, 2025). "The clusterin (CLU) gene is genetically associated with Alzheimer's disease (ad), and CLU levels have been shown to positively correlate with regional Aβ deposition in the brain, including in arteries from cerebral amyloid angiopathy (CAA) patients." (PMID 40919646, 2025). "The strongest association based on odds ratios in the Elsevier pathway was in amyloid beta clearance in Alzheimer’s disease (odds ratio (OR)=199.7, p=0.04), with CLU being the only gene associated with this pathway." (PMID 41552085, 2025). "CLU has been extensively associated with Alzheimer’s Disease; however, increasing evidence links this chaperone to Parkinson’s Disease (PD) as well." (PMID 40650133, 2025). "Variants in the CLU gene have been associated with the risk for late-onset Alzheimer’s disease, with elevated CLU protein levels observed in blood and CSF of Alzheimer’s disease patients." (PMID 40433620, 2025). "For both DLBTau− and DLBTau+ patients, clusterin (CLU), a major genetic risk factor for late-onset Alzheimer’s disease (AD), also exhibited a higher expression (FDR-adjusted p-value < 0.05) and was the second most elevated protein in both subgroups." (PMID 39696638, 2024). "Clusterin is upregulated in the brains of patients with Alzheimer’s disease and is a significant risk factor for Late-Stage AD." (PMID 38853911, 2024). "Overall, our data offers a novel mechanism for the association between clusterin as a genetic risk factor and Alzheimer’s disease myelin pathology." (PMID 38853911, 2024). "The sHsp clusterin is a secreted, extracellular holdase-type chaperone found to be a risk factor for Alzheimer’s disease accumulating in patient brains and plaques." (PMID 37731161, 2023). "Specific variants of the CLU gene are strongly associated with an increased risk of Alzheimer's disease and Parkinson's disease." (PMID 37195412, 2023). "Because clusterin and α2M are both associated with protein deposition diseases such as Alzheimer's disease, prion disease, and atherosclerosis, both chaperones have similar physiological roles." (PMID 36977730, 2023). "Alternative splicing has been implicated in the susceptibility of Alzheimer's disease (AD) and many genes associated with AD undergo alternative splicing, CLU being one of them." (PMID 37122381, 2023). "The C allele of rs11136000 variant in the clusterin (CLU) gene represents the third strongest known genetic risk factor for late-onset Alzheimer’s disease." (PMID 37494190, 2023). "CLU is now considered the third greatest risk gene for late onset Alzheimer’s disease (LOAD), after APOE and BIN1." (PMID 37047762, 2023). "There are similarities in the pathophysiological courses of PEX and Alzheimer’s disease and CLU rs1532278 variant has been reported to be significantly associated with late onset Alzheimer’s disease in a large cohort study." (PMID 36959561, 2023). "For instance, increased CLU expression in Alzheimer’s disease is associated with amyloid beta peptide aggregation in senile plaques." (PMID 37685987, 2023). "Clusterin is a multifunctional protein, which is associated with the pathogenesis and the development of Alzheimer’s disease (AD)." (PMID 36581903, 2022).
Alzheimer disease (continued). "Several pathways have been discovered possibly explaining CLU’s pathogenic function in Alzheimer’s disease." (PMID 36291661, 2022). "Primary structure of CLU is encoded by CLU gene which contains single nucleotide polymorphisms (SNP’s) associated with the risk of late-onset Alzheimer’s disease (LOAD)." (PMID 36581903, 2022). "Clusterin (CLU) is one of the most significant genetic risk factors for late onset Alzheimer’s disease (AD)." (PMID 36329114, 2022). "Following the discovery of single nucleotide polymorphisms in the CLU gene that contribute to the development of Alzheimer's disease, a possible role for clusterin in the pathogenesis of other neurodegenerative diseases was suggested." (PMID 36071866, 2022). "Among these, clusterin, a glycoprotein associated with Alzheimer's disease, binds α‐synuclein aggregated species and is present in Lewy bodies, intraneuronal aggregates mainly composed by fibrillary α‐synuclein." (PMID 33045109, 2021). "An example is the gene CLU, which is the third most significant genetic risk factor for the development of late-onset Alzheimer’s disease." (PMID 34326310, 2021). "Variants of the extracellular chaperone Clusterin are associated with Alzheimer’s disease (AD) and Clusterin levels are elevated in AD patient brains." (PMID 34381050, 2021). "Genome-wide association studies have established clusterin (CLU) as a genetic modifier for late-onset Alzheimer’s disease (AD)." (PMID 33517893, 2021). "The Alzheimer’s disease-associated trans-eQTL in the clusterin (CLU/APOJ) locus is also associated with the expression of genes of the complement cascade." (PMID 32012164, 2020). "We screen the 99% credible set of Alzheimer's disease (AD) GWAS variants identified at the clusterin (CLU) locus to identify a subset of likely causal variants, and employ GenIE to understand the impact of specific mutations on splicing efficiency." (PMID 33152068, 2020). "Clusterin (CLU) is one of the risk genes most associated with late onset Alzheimer’s disease (AD), and several genetic variants in CLU are associated with AD risk." (PMID 32992916, 2020). "We also used the high-resolution imaging technique array tomography to further assess the impact of ApoE4 and Alzheimer's disease on the synaptic localization of Aβ and clusterin and the related impact on the loss of synaptic density in Alzheimer’s disease." (PMID 31853523, 2019). "We found two lifespan candidate loci which were previously associated with Alzheimer’s disease: the newly identified EPHX2/CLU and, perhaps the most widely reported candidate lifespan locus: APOE." (PMID 31484785, 2019). "The effects of ApoE in Alzheimer's disease have long been studied but by comparison the study of the related apolipoprotein clusterin has been limited despite it too being a genetic risk factor for the disease." (PMID 31853523, 2019). "Several cohort studies and meta-analyses suggest that CLU gene rs11136000 variant is significantly associated with Alzheimer’s disease." (PMID 30909654, 2019). "Clusterin (CLU) or APOJ is a multifunctional glycoprotein that has been implicated in several physiological and pathological states, including Alzheimer’s disease (AD)." (PMID 30872998, 2019). "ApoER2 and VLDLR were recently identified as receptors for Clusterin (apolipoprotein J) which has been implicated in Alzheimer disease and cancer." (PMID 30304853, 2018). "Recently, the gene encoding clusterin (CLU) has consistently been associated with risk of Alzheimer’s disease." (PMID 29534716, 2018). "Clinical and epidemiological studies of older persons have implicated clusterin in Alzheimer's disease (AD) pathogenesis." (PMID 29324756, 2018). "Clusterin (CLU) has been associated with the clinical progression of Alzheimer’s disease (AD) and described as a potential AD biomarker in blood plasma." (PMID 29361679, 2018). "In Alzheimer’s disease, clusterin was found to be a risk factor in many genome wide association studies." (PMID 27861589, 2016).
Alzheimer disease (continued). "The Clusterin (CLU) gene, also known as apolipoprotein J (ApoJ), is currently the third most associated late-onset Alzheimer’s disease (LOAD) risk gene." (PMID 27229352, 2016). "For example, soluble CLU prevents the aggregation of amyloid β protein in Alzheimer’s disease and high levels of CLU mRNA have been associated with aging." (PMID 27507242, 2016). "Genome‐wide association studies have identified clusterin as one of the risk genes associated with Alzheimer's disease (AD)." (PMID 25940137, 2016). "Plasma clusterin is reported associated with the early pathology of Alzheimer's disease (AD) and longitudinal brain atrophy in subjects with MCI." (PMID 27516739, 2016). "Genome-wide association studies have provided compelling evidence for a role of genetic variation in the clusterin gene (CLU aka APOJ) in susceptibility of Alzheimer’s disease (AD)." (PMID 26179372, 2015). "The clusterin (CLU) gene has been identified as an important risk locus for Alzheimer’s disease (AD)." (PMID 26179372, 2015). "Large scaled genome-wide association studies in Caucasian and Asian populations have demonstrated a strong association between the single nucleotide polymorphisms (SNPs) in the clusterin gene and Alzheimer's disease." (PMID 25076422, 2014). "Polymorphism in the genomic region harboring the CLU gene (rs11136000) has been associated with the risk for Alzheimer’s disease (AD)." (PMID 24379779, 2013). "Genome-wide associated studies have linked the CLU gene with the risk of developing late-onset Alzheimer’s disease (AD)." (PMID 22906254, 2012). "The minor allele of rs11136000 within CLU is strongly associated with reduced Alzheimer's disease (AD) risk." (PMID 22506010, 2012). "The multifunctional glycoprotein clusterin has been associated with late-onset Alzheimer’s disease (AD)." (PMID 22906254, 2012). "Upregulation of clusterin expression is not only associated with amyloid deposits in Alzheimer disease but also with various other neurological disorders." (PMID 20420693, 2010). "Recently, two large genome wide association studies in Alzheimer disease (AD) have identified variants in three different genes (CLU, PICALM and CR1) as being associated with the risk of developing AD." (PMID 20209083, 2010). "Dysregulation of clusterin is linked to late-onset Alzheimer disease." (PMID 40781479, 2025). "Genes involved in cholesterol metabolism, such as APOE, CLU, and ATP‐binding cassette transporters, including apolipoprotein E, apolipoprotein J, and ATP‐binding cassette transporters, are linked to the pathophysiology of Alzheimer's disease." (PMID 41277170, 2025). "Mutations in the CLU gene are one of the most significant risk factors for Alzheimer's disease, and multiple studies implicate CLU as protecting brain cells from toxic Aβ oligomers by neutralising their toxicity and mediating their safe clearance from the brain." (PMID 37313660, 2023). "Although there are no studies on the relationship between intestinal dysbiosis and serum clusterin levels in patients with psoriasis, the changes in gut microbiome components and metabolites in patients with Alzheimer’s disease are associated with changes in the serum clusterin level." (PMID 37717073, 2023). "Clusterin also referred as apolipoprotein J (ApoJ), a small heat shock protein that acts as a molecular chaperone and promotes cell survival, has been largely reported in the literature associated with Alzheimer’s disease and other neurodegenerative diseases." (PMID 37004691, 2023). "The clusterin (CLU) rs11136000 CC genotype is a probable risk factor for Alzheimer’s disease (AD)." (PMID 37047762, 2023). "Moreover, CLU has been linked to Wnt signaling; the role of this signal transduction pathway in the development of Alzheimer’s disease has been extensively researched." (PMID 36291661, 2022).